P4HA1 (prolyl 4-hydroxylase subunit alpha 1)
Diseases named in the same sentence as P4HA1 in open-access papers (continued):
Sharing a sentence is not in itself a finding about the gene and the disease.
prostate carcinoma (14 papers, 2014 to 2025). A carcinoma that arises from epithelial cells of the prostate gland. "To further confirm the association between P4HA1 expression and prostate cancer progression, we analyzed P4HA1 protein levels in human prostate cancer tissues using tissue microarrays (TMA)." (PMID 38907027, 2024). "Studies have linked the onset and progression of prostate cancer to three genes related to hypoxia: P4HA1, ANGPLT4, and VEGFA." (PMID 38791417, 2024). "The overexpression of P4HA1, a gene encoding a collagen synthesis enzyme, has been associated with increased invasion and metastasis in various malignancies, including prostate cancer." (PMID 38791417, 2024). "In prostate cancer, P4HA1 expression levels were associated with disease progression." (PMID 32166002, 2020). "The development and progression of prostate cancer through the P4HA1 pathway involves facilitating the growth and survival of cancer cells, activating certain cellular signaling pathways, and controlling the activity of a key transcription factor HIF-1α." (PMID 38791417, 2024). "P4HA1 expression positively correlates with tumor stage and grade, with higher levels observed in prostate cancer tissue compared to healthy tissue." (PMID 38791417, 2024). "P4HA1 can also promote prostate cancer cell growth and tumor progression and is correlated with prostate cancer progression." (PMID 35812752, 2022). "Our study is corroborated through Oncomine co-expression analysis that shows CtBP1, EZH2 and P4HA1 are co- and over-expressed in prostate carcinoma samples." (PMID 25115393, 2014). "This study reveals multiple targets of therapeutic intervention in the P4HA1 pathway in prostate cancer." (PMID 25115393, 2014). "In the present study, we investigated the expression and role of prolyl hydroxylase P4HA1 in prostate cancer." (PMID 25115393, 2014). "Immunohistochemical analysis using tissue microarray demonstrated that P4HA1 expression was correlated with prostate cancer progression." (PMID 25115393, 2014). "In this study, we present evidence suggesting that overexpression of P4HA1 plays critical role in prostate cancer progression." (PMID 25115393, 2014). "In order to evaluate P4HA1-mediated effects in prostate cancer progression, we performed gene expression analysis using RNA from P4HA1 knockdown prostate cell lines." (PMID 25115393, 2014). "To determine the functional significance of P4HA1 overexpression in prostate cancer we perturbed P4HA1 levels in prostate cells and tested them in cell proliferation, migration and invasion assays." (PMID 25115393, 2014). "Together, these observations demonstrate the involvement of P4HA1 in the proliferation, migration and invasion of prostate cancer cells in vitro." (PMID 25115393, 2014). "Next, we tested cell motility after stable P4HA1 knockdown in prostate cancer cells using wound healing assay." (PMID 25115393, 2014). "We utilized both transient RNA interference and stable knockdown strategies targeting P4HA1 in aggressive prostate cancer cell lines, DU145 and PC3." (PMID 25115393, 2014). "Fluorescence in situ hybridization using P4HA1 locus specific FISH probe revealed copy number gain in aggressive prostate cancer cell line PC3." (PMID 25115393, 2014). "Our knockdown studies demonstrated that P4HA1 expression is required for prostate cancer cell proliferation and invasion." (PMID 25115393, 2014). "We investigated the potential role of P4HA1-induced MMP1 in prostate cancer invasion in vitro using either specific siRNA or MMP1 inhibitor (FN-439)." (PMID 25115393, 2014). "Using in vitro studies, we showed that P4HA1 plays a critical role in prostate cancer cell growth and tumor progression." (PMID 25115393, 2014). "In order to determine if P4HA1 is subject to regulation by miRs in prostate cancer, we utilized microRNA target prediction software programs TargetScan, miRanda and miRSearch V3.0." (PMID 25115393, 2014).
prostate carcinoma (continued). "Real-time qPCR analysis confirmed the overexpression of P4HA1 in metastatic prostate cancer tissues relative to benign prostate samples as did immunoblot analysis using P4HA1-specific antibody." (PMID 25115393, 2014). "Consistent with the results from cancer cell lines, metastatic prostate cancer tissue samples also expressed low miR-124 and high P4HA1 mRNA compared to benign samples." (PMID 25115393, 2014). "In this study, we characterized prolyl 4-hydroxylase, alpha polypeptide I (P4HA1) as overexpressed specifically in aggressive prostate cancer." (PMID 25115393, 2014). "Indeed, we observed a significant association between P4HA1 and MCT1 expression in prostate cancer patients’ specimens, suggesting that P4HA1 can have a role in lactate-rich prostate carcinomas." (PMID 38907027, 2024). "We examined whether LA-induced P4HA1 could help to potentiate the invasive ability of CAF-exposed prostate cancer cells." (PMID 38907027, 2024). "Notably, prostate cancer cases with genetic alteration of P4HA1 (>1% frequency) had copy number deletions." (PMID 35812752, 2022). "In a subset of prostate cancer we found copy number gain of P4HA1." (PMID 25115393, 2014). "Our studies provide a rationale for targeting P4HA1 in aggressive prostate cancer." (PMID 25115393, 2014). "With multiple MMP1 inhibitors in clinical trials, MMP1 could potentially serve as a surrogate target and benefit the prostate cancer patients that overexpress P4HA1." (PMID 25115393, 2014). "Similarly, elevated levels of P4HA1 protein was observed in metastatic prostate cancer cell lines relative to benign cell lines." (PMID 25115393, 2014). "Our data suggest that miR-124 targets P4HA1 and acts as tumor suppressor miR in prostate cancer." (PMID 25115393, 2014). "In this study, we show that P4HA1 is regulated by multiple mechanisms in prostate cancer." (PMID 25115393, 2014). "Similarly, a small subset of metastatic prostate cancer tissues were found to have copy number gains of P4HA1." (PMID 25115393, 2014). "Furthermore, our studies implicate a role for P4HA1 in prostate cancer progression and invasion in vitro and in vivo." (PMID 25115393, 2014). "Our observations suggest that P4HA1 plays a critical role in prostate cancer progression and could serve as a viable therapeutic target." (PMID 25115393, 2014). "In addition, FLRT3- (a P4HA1-down-regulated gene) rescue experiments demonstrated its role in prostate cancer migration as assessed by the wound healing assay." (PMID 25115393, 2014). "Next, to determine whether miR-124 represses P4HA1 expression, we treated prostate cancer cells with precursor miRs, miR-124 as well as other miRs such as miR-23a, 23b, 29a, 29b, 29c, 122, and 499a and measured P4HA1 protein levels." (PMID 25115393, 2014). "Here, we show the overexpression of P4HA1 in aggressive prostate cancer." (PMID 25115393, 2014). "However, P4HA2 mRNA expression levels were relatively lower than P4HA1 in malignant prostate cancer tissues and cell lines." (PMID 25115393, 2014). "Similarly, we observed decrease in cell proliferation in androgen-dependent LnCaP cells, suggesting a broad role for miR-124 and its target P4HA1 in both castration-resistant and hormone-sensitive prostate cancer cells." (PMID 25115393, 2014). "In prostate cancer, P4HA1 could promote prostate cancer metastasis via regulating MMP1 expression." (PMID 34659558, 2021). "We investigated the expression of P4HA1 protein in large number of prostate cancer samples by immunohistochemical (IHC) analysis that showed weak or no reactivity in benign tissues but strong staining in the aggressive prostate cancer tissue and metastatic prostate tumors." (PMID 25115393, 2014). "Thus, as an enzyme, P4HA1 can serve as a promising therapeutic target in prostate cancer." (PMID 25115393, 2014). "Additionally, overexpression of P4HA1 promotes tumor invasion and metastasis via the P4HA1-MMP1 pathway in prostate cancer." (PMID 28415787, 2017).
prostate carcinoma (continued). "CAM was performed using P4HA1 knockdown DU145 and PC3 prostate cancer cells." (PMID 25115393, 2014). "qPCR analysis in prostate cancer cell lines showed that benign prostate epithelial cell line PrEC expressed greater amounts of miR-124 and lower P4HA1 levels in contrast to aggressive prostate cancer cell lines DU145 and PC3 that express lower miR-124 and higher P4HA1 levels." (PMID 25115393, 2014).
melanoma (13 papers, 2016 to 2025). A malignant, usually aggressive tumor composed of atypical, neoplastic melanocytes. "We found that the highest alteration frequency of P4HA1 (>4%) was observed in melanoma patients, in which “Mutation” was the primary type." (PMID 34966739, 2021). "In melanoma, collagen P4H enzymes are reported to be bifunctional growth and tumor invasiveness regulators, and P4H family members, including P4HA1, were found to be overexpressed and associated with poor clinical outcomes." (PMID 32166002, 2020). "In our gene set enrichment analysis, we found that P4HA1 is a part of a gene expression signature associated with hypoxia and glycolysis both in melanoma cell lines and in clinical melanoma primary tumors." (PMID 32053263, 2020). "P4HA1 variant 1 (encoding isoform 1) as well as variants 2 and 3 (encoding isoform 2) were expressed at a similar or higher level in most melanoma cell lines compared to fibroblasts." (PMID 32053263, 2020). "We first analyzed the mRNA expression levels of all P4HA1 transcript variants in melanoma cell lines and in primary cultures of human embryonic fibroblasts, microvascular endothelial cells, and normal melanocytes." (PMID 32053263, 2020). "Among others, high mRNA expression of the hypoxia‐regulated P4HA1 gene, encoding the catalytic subunit of prolyl 4‐hydroxylase, correlated highly significantly with shorter patient survival in an independent primary melanoma dataset." (PMID 32053263, 2020). "To reveal which processes P4HA1 may be associated with in melanoma, we studied which genes show correlated mRNA expression to that of P4HA1 in a panel of 62 melanoma cell lines (E‐GEOD‐7127)." (PMID 32053263, 2020). "Interestingly, we found several genes involved in the ECM modification, such as FN1 and P4HA1, which may be expressed by both melanoma and stromal cells, to be associated with metastasis and patient prognosis." (PMID 26918341, 2016). "P4ha1 is one of the metabolic-related genes for predicting poor clinical prognosis and immune microenvironment in primary melanomas, lung adenocarcinoma, and squamous cell carcinoma of the head and neck." (PMID 39272995, 2024). "To explore the function of P4HA1 in melanoma, we silenced the expression of P4HA1 in WM239 melanoma cells." (PMID 32053263, 2020). "P4HA1 was mainly expressed by melanoma cells but fairly often also by fibroblasts surrounding the melanoma cell nests, and by fibroblasts in the upper dermis." (PMID 32053263, 2020). "We chose to study further P4HA1 in melanoma progression to assess its potential as a prognostic marker and therapeutic target." (PMID 32053263, 2020). "At the protein level, embryonic fibroblasts showed higher expression of P4HA1 compared to the melanoma cell lines." (PMID 32053263, 2020). "We then studied the effect of P4HA1 on melanoma cell invasion in 3D Matrigel and found that the knockdown of P4HA1 markedly reduced the invasive growth of WM239 cells." (PMID 32053263, 2020). "Taken together, P4HA1 is a highly interesting potential prognostic marker and therapeutic target, influencing many aspects of melanoma tumor progression." (PMID 32053263, 2020). "We also analyzed the expression and localization of P4HA1 in primary melanoma tissues (n = 27) by immunohistochemical staining." (PMID 32053263, 2020). "As we found P4HA1 knockdown to reduce the secretion of CTHRC1 in melanoma cells in vitro, and our previous results have shown that CTHRC1 is localized in the blood vessels in human melanomas, we further studied the expression of CTHRC1 in the xenograft tumors." (PMID 32053263, 2020). "Our melanoma xenograft model suggested that P4HA1 knockdown also reduces melanoma invasion in vivo as well as the deposition of collagens, particularly COL‐IV, in the interstitial ECM and in the basement membranes of tumor blood vessels." (PMID 32053263, 2020). "We studied further the significance of one of the genes, prolyl 4‐hydroxylase subunit alpha 1 (P4HA1), in melanoma progression." (PMID 32053263, 2020).
melanoma (continued). "Here, we show that P4HA1 knockdown reduced CTHRC1 secretion in melanoma cells in vitro and CTHRC1 protein deposition around tumor blood vessels in vivo." (PMID 32053263, 2020). "We also found that genes that correlated with P4HA1 mRNA expression in primary melanoma tissues (n = 103, the Cancer Genome Atlas, TCGA) were over‐represented in hypoxia, glycolysis, and MTORC1 signaling." (PMID 32053263, 2020). "As fibroblasts have been reported to be important producers of P4HA1, we wanted to confirm that P4HA1 is also expressed by melanoma cells." (PMID 32053263, 2020). "Taken together, P4HA1 is an interesting potential prognostic marker and therapeutic target in primary melanomas, influencing many aspects of melanoma tumor progression." (PMID 32053263, 2020). "We studied further the significance of one of these genes, P4HA1, in melanoma progression and show that P4HA1 depletion in melanoma cells reduced cell adhesion, invasion, and viability in vitro." (PMID 32053263, 2020). "Of our topmost novel prognostic marker genes for primary melanomas, P4HA1 seemed the most interesting as its expression was largely tumor cell‐specific and upregulated in melanoma cell lines compared to normal melanocytes." (PMID 32053263, 2020). "This was also evident in our xenograft model, where knockdown of P4HA1 in the melanoma cells led to reduced collagen deposition in the tumor tissues." (PMID 32053263, 2020). "To find possible targets of P4HA1 in melanoma cell lines, we checked the expression levels of genes encoding collagen domain‐containing proteins in a publicly available microarray data of 62 melanoma cell lines (E‐GEOD‐7127)." (PMID 32053263, 2020). "We further found that P4HA1 depletion inhibited the invasion of melanoma cells in vitro and in vivo." (PMID 32053263, 2020). "As P4HA1 expression correlated with poor patient survival in human primary melanoma samples, we unexpectedly observed that P4HA1 knockdown increased tumor size in nude mice." (PMID 32053263, 2020). "In our analyses of primary melanoma tumors, both the tumor cells and the stromal fibroblasts produced P4HA1, although the tumor cells appeared to be the main producers." (PMID 32053263, 2020). "We further studied the function of P4HA1 in melanoma by knocking it down and analyzing the effect on melanoma cell adhesion, invasion, and viability in vitro and tumorigenesis in vivo." (PMID 32053263, 2020). "High P4HA1 gene and protein expression values have been recently described as a prognostic predictor in head and neck squamous cell carcinoma as well as primary melanomas." (PMID 35269711, 2022). "In melanoma, depletion of P4HA1 reduces cell adhesion, invasion and in vitro survival, and in xenotransplantation models, knockdown of P4HA1 reduces the invasion of melanoma in vivo and the deposition of collagen in interstitial ECM and tumor vascular basement membranes." (PMID 34217310, 2021). "We found that melanoma patients had the highest alteration frequency of P4HA1 (>4%)." (PMID 34966739, 2021). "Also, laminin α5, which was downregulated in the P4HA1‐knockdown cells, strongly promotes melanoma cell migration." (PMID 32053263, 2020). "P4HA1 depletion in melanoma cells reduced cell adhesion, invasion, and viability in vitro." (PMID 32053263, 2020). "One of them, prolyl 4‐hydroxylase subunit alpha 1 (P4HA1), proved critical for the invasion and survival of melanoma cells and the deposition of collagens (stained in blue) and CTHRC1 in the extracellular matrix and tumor blood vessel walls, maintaining their integrity." (PMID 32053263, 2020). "Our preliminary results from immunohistochemical staining of primary melanomas suggest that, in addition to P4HA1 mRNA levels, also high P4HA1 protein expression may be associated with increased metastasis and mortality and may serve as a prognostic factor (data not shown)." (PMID 32053263, 2020).
melanoma (continued). "In melanoma and other cancers, BNIP3 and P4HA1 are induced under hypoxic conditions, promoting tumor growth and progression." (PMID 41000875, 2025). "As P4HA1 is needed for collagen secretion and deposition in the ECM, we first studied the effect of P4HA1 downregulation on melanoma cell adhesion in uncoated wells in serum‐free medium." (PMID 32053263, 2020). "Altogether, therapeutic targeting of P4HA1 (and P4HA2) is an interesting possibility for the treatment of aggressive melanomas, and other cancers, but more specific inhibitors, are still needed." (PMID 32053263, 2020). "To further elucidate the function of P4HA1 in melanoma, we performed genomewide gene expression analysis of the WM239 P4HA1‐KD cells." (PMID 32053263, 2020). "We then analyzed the protein expression levels of human embryonic fibroblasts and two melanoma cell lines WM239 and SKMEL‐28, which expressed P4HA1 mRNA at high level." (PMID 32053263, 2020). "Further, P4HA1 knockdown reduced the secretion of collagen triple helix repeat containing 1 (CTHRC1), an important mediator of melanoma cell migration and invasion, in vitro and its deposition around tumor blood vessels in vivo." (PMID 32053263, 2020). "Overexpression of P4HA1 has previously been seen in TNBC-BC, head and neck squamous cell carcinomas (HNSCC), prostate, melanoma, and gastric cancer." (PMID 33692831, 2021). "In our melanoma model, the silencing of P4HA1 did not appear to interfere with tumor cell proliferation in vitro or in vivo, as assessed by staining with the cell proliferation marker Ki‐67." (PMID 32053263, 2020).